FAT3 (FAT atypical cadherin 3)
Description:
May play a role in the interactions between neurites derived from specific subsets of neurons during development.
Synonyms: hFat3; CDHF15; KIAA1989; CDHR10
Tractability: Antibody: UniProt predicts a signal peptide or a membrane-spanning region; its Gene Ontology location is reachable by antibodies, with medium confidence. PROTAC: its protein half-life has been measured.
Gene: Protein-coding gene on chromosome 11 (92,224,818 to 92,896,473, forward strand). Ensembl gene ENSG00000165323.
Subcellular location: Membrane
Subcellular location (Human Protein Atlas): Cell Junctions
Gene Ontology:
Molecular function: protein binding; calcium ion binding
Biological process: cell-cell adhesion mediated by cadherin; anatomical structure formation involved in morphogenesis; animal organ morphogenesis; cell adhesion; cell morphogenesis; homophilic cell-cell adhesion; neuron migration; regulation of plasma membrane bounded cell projection organization
Cellular component: adherens junction; plasma membrane; dendrite; membrane; neuron projection
Genetic constraint (gnomAD): Loss-of-function variants: 90 observed, 309.23 expected, observed/expected ratio (o/e) 0.29, 90% interval 0.24 to 0.35. The upper end of that interval is the gene's LOEUF score, 0.35, which puts it in group 1 of 6, group 1 being the genes least tolerant of losing a copy. Missense variants: 5,347 observed, 5,899.8 expected, observed/expected ratio (o/e) 0.91, 90% interval 0.88 to 0.93. Synonymous variants: 2,289 observed, 2,270.9 expected, observed/expected ratio (o/e) 1.01, 90% interval 0.97 to 1.04.
Homologues: Orthologues: chimpanzee FAT3 (99% identical), macaque FAT3 (99% identical), dog FAT3 (96% identical), rabbit FAT3 (95% identical), rat Fat3 (93% identical), mouse Fat3 (92% identical), tropical clawed frog fat3 (79% identical), zebrafish fat3a (63% identical), zebrafish fat3b (55% identical), Caenorhabditis elegans hmr-1 (15% identical), Drosophila melanogaster stan (12% identical), Caenorhabditis elegans fmi-1 (10% identical), and 1 more. Paralogues in human: FAT1 (52% identical), FAT2 (40% identical), FAT4 (27% identical), CELSR1 (13% identical), CELSR3 (13% identical), CELSR2 (13% identical).
Diseases named in the same sentence as FAT3 in open-access papers:
FAT3 is named in the same sentence as 66 diseases in open-access papers, as found by Europe PMC text mining. Sharing a sentence is not in itself a finding about the gene and the disease. The quoted sentences say what the papers report.
ovarian carcinoma (6 papers, 2021 to 2024). A malignant neoplasm originating from the surface ovarian epithelium. "Studies have shown that FAT3 was a key mutation gene in multiple tumors, including ovarian cancer, breast cancer, lung adenocarcinoma, and pancreatic acinar cell carcinoma." (PMID 33816234, 2021). "This disparity implies that FAT3 mutations may have a more pronounced impact on the tumorigenesis or progression of ovarian cancer in the low‐risk subgroup." (PMID 38520216, 2024).
breast carcinoma (5 papers, 2020 to 2025). "The low expression of FAT3 can enhance the chemotherapy sensitivity of breast cancer cells and can be used as a marker to predict the effect of breast cancer drug treatment." (PMID 33968045, 2021). "Only one gene, FAT3, mutated in more than 5% stage III-IV cancer samples, and there is no report in literature to our knowledge on this gene’s relation with breast cancer relapses and metastasis." (PMID 33193655, 2020). "FAT3, MUC16, and SYNE1 have also been mentioned as common mutant genes in breast cancer in previous studies, but there is no specific report on whether they affect the development and prognosis of breast cancer." (PMID 33968045, 2021).
lung adenocarcinoma (4 papers, 2021). A carcinoma that arises from the lung and is characterized by the presence of malignant glandular epithelial cells. "Although FAT3 gene mutations are common in many cancers, including lung adenocarcinoma, there are few studies on the association between FAT3 gene and immunotherapy." (PMID 35069585, 2021). "Nevertheless, we believe that the data of this paper has proved that in patients with lung adenocarcinoma, the co-mutation status of FAT3 and LRP1B deserves further attention and research." (PMID 35069585, 2021). "Studies have reported that the whole genome expression of lung tumor cell populations of transgenic mice was analyzed by laser capture microdissection, and it was found that FAT3 mRNA was significantly down-regulated in lung adenocarcinoma." (PMID 33816234, 2021). "In summary, co-mutation of FAT3 and LRP1B is a promising useful biomarker for predicting the efficacy of immunotherapy, which can improve the clinical efficiency of practicing precision medicine in lung adenocarcinoma patients." (PMID 35069585, 2021). "This research provides evidence that co-mutation of FAT3 and LRP1B may be a very promising novel biomarker for screening candidates of ICIs therapy in lung adenocarcinoma and lays a preliminary foundation for subsequent further exploration." (PMID 35069585, 2021). "After stepwise screening, we obtained FAT3 and LRP1B, two key genes closely related to the immunogenicity, cytotoxicity and immunotherapy response of lung adenocarcinoma patients." (PMID 35069585, 2021). "Taken together, these data suggest that the co-mutation of FAT3 and LRP1B defines a unique subset and may be a promising novel biomarker for screening candidates for ICIs therapy of lung adenocarcinoma." (PMID 35069585, 2021).
colorectal cancer (3 papers, 2009 to 2021). A primary or metastatic malignant neoplasm that affects the colon or rectum. "Recently, FAT atypical cadherin 3 (FAT3), kinectin 1 (KTN1), discs large homolog 2 (DLG2) and deleted in colorectal cancer (DCC) have been reported to be associated with the function of the human mesolimbic reward system, which is the neurobiological basis of drug addiction." (PMID 27676367, 2016).
lung carcinoma (3 papers, 2022 to 2024). "A recent study showed that the lung cancer patients with co-mutation of FAT3 and LRP1B had significantly prolonged immunotherapy PFS, which indicated that co-mutation of FAT3 and LRP1B is a promising biomarker to predict the efficacy of immunotherapy." (PMID 35372348, 2022).
melanoma (3 papers, 2018 to 2023). A malignant, usually aggressive tumor composed of atypical, neoplastic melanocytes. "In the FAT3 mutation samples, three pathways of dorso-ventral axis formation, glioma, and melanoma were significantly enriched." (PMID 33968045, 2021).
metastatic tumor (3 papers, 2016 to 2022). "The mutational frequencies of CDKN2B (14.8% vs. 0%, p = 0.001), FAT3 (7.4% vs. 0%, p = 0.041), MTAP (13% vs. 1.6%, p = 0.023), and SMAD4 (31.4% vs. 15.6%, p = 0.049) in metastatic tumors were significantly higher than that in primary tumors." (PMID 35664782, 2022). "Importantly, the mutational frequency of CDKN2B (14.8% vs. 0%, p = 0.001), FAT3 (7.4% vs. 0%, p = 0.041), MTAP (13% vs. 1.6%, p = 0.023), and SMAD4 (31.4% vs. 15.6%, p = 0.049) in metastatic tumors were significantly higher than those in primary tumors." (PMID 35664782, 2022). "Notably, CDKN2B and FAT3 alterations occurred only in patients with metastatic tumors." (PMID 35664782, 2022). "Notably, CDKN2B and FAT3 alterations occurred only in metastatic tumors." (PMID 35664782, 2022). "Other genes, such as BCORL1 (OVA_003), CASP3 (OVA_047), CHD2 (OVA_013), FAT3 (OVA_365) and LZTR1 (OVA_378), were heterogeneous, having differing clonality in the primary versus the metastatic tumours." (PMID 32099096, 2020). "The mutational frequencies (metastatic vs. primary) of CDKN2B (14.8% vs. 0%, p = 0.001), FAT3 (7.4% vs. 0%, p = 0.041), MTAP (13% vs. 1.6%, p = 0.023), and SMAD4 (31.4% vs. 15.6%, p = 0.049) in metastatic tumors were significantly higher than in primary tumors." (PMID 35664782, 2022).
Ataxia (2 papers, 2020 to 2023). Ataxia refers to impaired coordination of voluntary muscle movement. "For example, FAT3 gene mutations are associated with Spinocerebellar Ataxia (SCA), and is more highly expressed in CB astrocytes particularly of older donors." (PMID 37217978, 2023). "Since defects in Fat3 gene are associated with several neuropsychiatric diseases, such as schizophrenia, autism, and ataxia, our finding may provide a hint that links microglial dysregulations to the onset of these diseases." (PMID 32868309, 2020).
lymph node metastasis (2 papers, 2020 to 2024). "tested samples of MPLC with lymph node metastasis (LNM) and found that the genes with the highest mutation frequencies in this pair were MUC16, FLNA, MUC4, FAT3, SETD2, and CALR, which implied that MPLC with LNM may have a unique mutation spectrum." (PMID 39411141, 2024). "Other factors like FAT3, APC, PTPRD (P = 0.01), lymph-node metastasis, EPHA3, TERT, and STK11 (P = 0.05) that have been found to be related to TMB distribution." (PMID 33996530, 2020).
small cell lung carcinoma (2 papers, 2021). Small cell lung cancer (SCLC) is a highly aggressive malignant neoplasm, accounting for 10-15% of lung cancer cases, characterized byrapid growth, and early metastasis. "FAT3 is a member of the family of human homologs to the Drosophila melanogaster transmembrane receptor for Hippo signaling and tumor-suppressor fat 49 and showed a significant association with TMB-high in small cell lung cancer." (PMID 33754015, 2021).
acinar cell carcinoma (1 paper, 2015). "Moreover, we identified germline missense mutations in FAT1 and FAT3 resulting in loss of the wild-type allele, which suggests that these germline mutations are likely to be selected and to contribute to the phenotype of acinar cell carcinoma." (PMID 25743105, 2015).
acral melanoma (1 paper, 2022). "FAT3 mutation was observed in 20% (3/15) patients with acral melanoma, ranking only second to NRAS." (PMID 35688842, 2022).
adenoma (1 paper, 2017). A neoplasm arising from the epithelium. "Previously unreported rs7944251 of FAT tumor suppressor homolog 3 (FAT3) was associated with reduced risk of advanced adenoma (OR=0.66, P=3.97×10-7) and the SNP was also selected when comparing advanced adenomas with the combined control group (B vs. CD)." (PMID 29228715, 2017).
developmental and epileptic encephalopathy (1 paper, 2024). An epilepsy associated with developmental impairment that may be due to either the underlying etiology or the superimposed epileptic activity, or both. "Within the cohort of patients experiencing developmental and epileptic encephalopathy (DEE), WES has revealed genetic variants in novel genes (FGF12, GABBR1, GABBR2, ITPA, KAT6A, PTPN23, RHOBTB2, SATB2) and candidate epilepsy-associated genes (CAMTA1, FAT3, GABRA6, HUWE1, PTCHD1)." (PMID 39523358, 2024).
embryonic carcinoma (1 paper, 2022). "To test if Fat3 affects the protein stability of Yap, we checked the protein level of Yap in the condition of Fat3 knockdown in P19 mouse embryonic carcinoma cells that were harvested 48 h after transfection." (PMID 36042367, 2022).
esophageal adenocarcinoma (1 paper, 2017). A malignant tumor with glandular differentiation arising predominantly from Barrett mucosa in the lower third of the esophagus. "FAT3 gene and PTGDR gene, both are shown to be associated significantly (p- value = 8.41E–04) with esophageal adenocarcinoma by IPA analysis." (PMID 28410234, 2017).
hyperparathyroidism (1 paper, 2023). Hyperfunction of the parathyroid glands resulting in the overproduction of parathyroid hormone. "The cohort was screened for gene variants of ADCK1, CCD1, FAT3, and THRAP3 that have previously been associated with PC as described in the literature but that were not included in the BpG hyperparathyroidism gene panel assessment." (PMID 36900197, 2023).
hypopituitarism (1 paper, 2019). A condition of diminution or cessation of secretion of one or more hormones from the anterior pituitary gland. "The duplication region 11q14.3-q21 encompassing MNTR1B and FAT3 co-occurred with duplication Xq27.3 encompassing the SOX3 gene, which was previously linked to the etiology of ID, hypopituitarism, and speech disorders, but not ASD." (PMID 30647996, 2019).
Malignant Skin Tumor (1 paper, 2021). "“Malignant Skin Tumor DN” showed that the mechanism of FAT3 mutation in the occurrence and development of ESCA was related to that of malignant skin." (PMID 33816234, 2021).
non-small cell lung carcinoma (1 paper, 2021). A group of at least three distinct histological types of lung cancer, including non-small cell squamous cell carcinoma, adenocarcinoma, and large cell carcinoma. "The human surfactant protein C promoter helps to regulate the expression of Fat3, and its expression is downregulated in non-small cell lung cancer." (PMID 34070222, 2021).
oral cancer (1 paper, 2022).
pancreatic tumor (1 paper, 2021). "The point mutation of FAT3 can cause pancreatic tumor in human cancer." (PMID 33816234, 2021).
renal carcinoma (1 paper, 2018). A carcinoma arising from the epithelium of the renal parenchyma or the renal pelvis. "Other gene mutations, such as FANCD2, FAT3, KDM6A, KDR, TET2, and TSC2, occurred twice in this MA cohort, which was quite different from other common types of renal carcinoma." (PMID 30111351, 2018).
scoliosis (1 paper, 2022). A congenital or acquired spinal deformity characterized by lateral curvature of the spine. "Interestingly, two FAT3 variants rs139595720 (genotype A/G) and rs80293525 (genotype C/T) were enriched in scoliosis ≥ 40° (4.5% and 2.7% respectively) compared to < 40° (1.4% and 0.7%) and controls (1.2% and 0.8%)." (PMID 35853984, 2022). "Interestingly, two FAT3 variants, rs139595720 (genotype A/G) and rs80293525 (genotype C/T), were enriched in severe scoliosis cases (4.5% and 2.7% respectively) compared to milder cases (1.4% and 0.7%) and healthy controls (1.6% and 0.8%)." (PMID 35853984, 2022). "As mentioned, two FAT3 variants (rs139595720 and rs187159256) are associated with scoliosis severity as demonstrated by the higher frequencies of the heterozygous genotypes in severe scoliosis (≥ 40°) compared to moderate scoliosis (< 40°) and healthy controls." (PMID 35853984, 2022).
serous ovarian cancers (1 paper, 2014). "In addition, this panel is targeting “hotspot” region of genes that are frequently mutated in human cancer thus other infrequently altered genes but of significance to serous ovarian cancers might have been excluded such as ARID1A, BRCA1, BRCA2, CSMD3, NF1, CDK12, FAT3 and GABRA6." (PMID 25404506, 2014).
Skin Tumor (1 paper, 2021). "GSEA analysis showed that samples with FAT3 mutation enriched in “ERBB2 Breast Preneoplastic UP”, “Kras Oncogenic Signature”, “Malignant Skin Tumor DN”, “MCV6 LCP With H3K27ME3”, and “MET Signaling”." (PMID 33816234, 2021).
Strabismus (1 paper, 2021). A misalignment of the eyes so that the visual axes deviate from bifoveal fixation. "Despite the small sample study, we were able to identify four genes (FAT3, KCNH2, CELSR1, TTYH1) with causative associations with strabismus." (PMID 33435129, 2021). "As a result, we found risk variants in four genes (FAT3, KCNH2, CELSR1, and TTYH1) in five families, suggesting their role in development of familial strabismus." (PMID 33435129, 2021).
triple-negative breast carcinoma (1 paper, 2021). An invasive breast carcinoma which is negative for expression of estrogen receptor (ER), progesterone receptor (PR), and human epidermal growth factor receptor 2 (HER2). "We found that FAT3 can be used as a risk predictor gene for triple-negative breast cancer and can be used as a target gene for further in-depth research." (PMID 33968045, 2021). "In addition, survival analysis showed that FAT3 was a mutant gene related to prognosis, and its high expression was significantly correlated with poor prognosis in triple-negative breast cancer patients." (PMID 33968045, 2021).